LRP5 (LDL receptor related protein 5)
Description:
Acts as a coreceptor with members of the frizzled family of seven-transmembrane spanning receptors to transduce signal by Wnt proteins. Activates the canonical Wnt signaling pathway that controls cell fate determination and self-renewal during embryonic development and adult tissue regeneration. In particular, may play an important role in the development of the posterior patterning of the epiblast during gastrulation (By similarity). During bone development, regulates osteoblast proliferation and differentiation thus determining bone mass. Mechanistically, the formation of the signaling complex between Wnt ligand, frizzled receptor and LRP5 coreceptor promotes the recruitment of AXIN1 to LRP5, stabilizing beta-catenin/CTNNB1 and activating TCF/LEF-mediated transcriptional programs. Acts as a coreceptor for non-Wnt proteins, such as norrin/NDP. Binding of norrin/NDP to frizzled 4/FZD4-LRP5 receptor complex triggers beta-catenin/CTNNB1-dependent signaling known to be required for retinal vascular development. Plays a role in controlling postnatal vascular regression in retina via macrophage-induced endothelial cell apoptosis (By similarity).
Synonyms: LRP-5; LRP-7; LR3; LRP7; BMND1; HBM; OPS; OPTA1; VBCH2; EVR4; EVR1; OPPG; PCLD4
Tractability: Antibody: its Gene Ontology location is reachable by antibodies, with high confidence; UniProt predicts a signal peptide or a membrane-spanning region. PROTAC: ubiquitination databases record sites on it.
Gene: Protein-coding gene on chromosome 11 (68,312,447 to 68,449,275, forward strand). Ensembl gene ENSG00000162337.
Subcellular location: Membrane; Endoplasmic reticulum
Pathways (Reactome):
Signal Transduction: Disassembly of the destruction complex and recruitment of AXIN to the membrane; Negative regulation of TCF-dependent signaling by WNT ligand antagonists; Regulation of FZD by ubiquitination; TCF dependent signaling in response to WNT
Disease: Signaling by LRP5 mutants; Signaling by RNF43 mutants
Gene Ontology:
Molecular function: coreceptor activity; protein binding; toxin transmembrane transporter activity; Wnt receptor activity; Wnt-protein binding
Biological process: adipose tissue development; bone marrow development; bone morphogenesis; canonical Wnt signaling pathway; cholesterol homeostasis; glucose catabolic process; negative regulation of osteoblast differentiation; Norrin signaling pathway; positive regulation of cell population proliferation; positive regulation of DNA-templated transcription; positive regulation of fat cell differentiation; positive regulation of mesenchymal cell proliferation; positive regulation of mitotic nuclear division; positive regulation of transcription by RNA polymerase II; regulation of blood pressure; retina morphogenesis in camera-type eye; retinal blood vessel morphogenesis; nervous system development; positive regulation of osteoblast differentiation; animal organ morphogenesis; bone development; extracellular matrix-cell signaling; positive regulation of cell cycle; positive regulation of cell differentiation; regulation of osteoblast differentiation; and 3 more
Cellular component: endoplasmic reticulum; plasma membrane; receptor complex; membrane; Wnt signalosome; Wnt-Frizzled-LRP5/6 complex
Genetic constraint (gnomAD): Loss-of-function variants: 60 observed, 154.44 expected, observed/expected ratio (o/e) 0.39, 90% interval 0.31 to 0.48. The upper end of that interval is the gene's LOEUF score, 0.48, which puts it in group 2 of 6, group 1 being the genes least tolerant of losing a copy. Missense variants: 1,891 observed, 2,388.1 expected, observed/expected ratio (o/e) 0.79, 90% interval 0.76 to 0.82. Synonymous variants: 954 observed, 1,027.6 expected, observed/expected ratio (o/e) 0.93, 90% interval 0.88 to 0.98.
Gene-disease validity (ClinGen):
ClinGen rates the evidence that LRP5 causes each of these diseases.
LRP5-related exudative vitreoretinopathy (autosomal recessive): Definitive. Any exudative vitreoretinopathy with or without osteoporosis caused by variants in the LRP5 gene.
polycystic liver disease 4 with or without kidney cysts (autosomal dominant): Limited. An autosomal dominant disease characterized by adult-onset of liver cysts arising from the bile duct epithelium, caused by heterozygous mutation in the LRP5 gene.
Homologues: Orthologues: macaque LRP5 (99% identical), chimpanzee LRP5 (99% identical), dog LRP5 (96% identical), pig LRP5 (96% identical), guinea pig LRP5 (95% identical), rat Lrp5 (95% identical), mouse Lrp5 (94% identical), tropical clawed frog lrp5 (82% identical), zebrafish lrp5 (75% identical). Paralogues in human: LRP6 (70% identical), LRP4 (37% identical), LRP1 (29% identical), LRP1B (27% identical), LRP2 (26% identical), VLDLR (12% identical), LRP8 (12% identical), EGF (10% identical), NID1 (9% identical), NID2 (8% identical), LRP10 (5% identical), and 2 more.
Diseases named in the same sentence as LRP5 in open-access papers:
LRP5 is named in the same sentence as 212 diseases in open-access papers, as found by Europe PMC text mining. Sharing a sentence is not in itself a finding about the gene and the disease. The quoted sentences say what the papers report.
osteoporosis (169 papers, 2007 to 2026). A condition of reduced bone mass, with decreased cortical thickness and a decrease in the number and size of the trabeculae of cancellous bone (but normal chemical composition), resulting in increased fracture incidence. "Variants in the LRP5 gene are particularly associated with osteoporosis-pseudoglioma syndrome, characterized by severe osteoporosis and ocular abnormalities." (PMID 40821177, 2025). "Complete loss of the LRP5 gene in humans causes osteoporosis pseudoglioma, a syndrome characterized by early-onset osteoporosis and changes in retinal vascularization." (PMID 40932232, 2025). "Loss-of-function mutations in LRP5 were associated with osteoporosis-pseudoglioma syndrome, highlighting the importance of the WNT signalling pathway." (PMID 40772209, 2025). "Given that these two cases involve LRP5 gene mutations associated with monogenic osteoporosis and a three-year history of BP therapy, the feasibility of utilizing genetic risk scores prior to initiating BP therapy should be investigated." (PMID 40821177, 2025). "LRP5 encodes low-density lipoprotein receptor-related protein 5, which is necessary for bone and eye development; dysfunction in this gene is linked to osteoporosis–pseudoglioma syndrome and familial exudative vitreoretinopathy (FEVR)." (PMID 40428427, 2025). "Mutations in LRP5, a gene encoding a co-receptor in the Wnt/β-catenin signaling pathway crucial for osteoblast differentiation and activity, are associated with osteoporosis-pseudoglioma syndrome (OPPG)." (PMID 41517371, 2025). "Loss-of-function mutations in LRP5 have been found to cause low bone mass and lead to osteoporosis-pseudoglioma syndrome, which presents with osteoporosis and eye defects." (PMID 40772209, 2025). "Mutations in the LRP5 gene can cause primary osteoporosis by reducing Wnt signaling activity, which is a critical pathway for bone formation and remodeling." (PMID 40821177, 2025). "Mutations in LRP5 lead to distinct phenotypic outcomes, ranging from osteoporosis to excessive bone formation, and contribute to congenital retinal disorders, neurodevelopmental defects, and cancers." (PMID 40940800, 2025). "Loss-of-function variants can cause osteoporosis-pseudoglioma syndrome, while gain-of-function variants result in a high bone mass phenotype, referred to as high bone mineral density LRP5 (LRP5 HBM)." (PMID 40585686, 2025). "The gain of function mutation in LRP5 results in increased bone density, whereas its loss of function mutation causes osteoporosis-pseudoglioma syndrome." (PMID 40940800, 2025). "Only when leveraging BMD, we identified a locus near LRP5 at a 1% cFDR, for which loss-of-function mutations are associated with osteoporosis and gain-of-function mutations with higher bone mass and craniosynostosis." (PMID 40087503, 2025). "Pathologically, both loss-of-function and gain-of-function mutations in LRP5 produce distinct phenotypes, ranging from osteoporosis-pseudoglioma syndrome to high bone mass disorders." (PMID 40940800, 2025). "We report AFFs in nine-year-old identical twins known to have LRP5 gene mutation-related osteoporosis treated with BPs." (PMID 40821177, 2025). "Loss-of-function mutations in LRP5 decrease signalling through Wnt pathway, leading to osteoporosis." (PMID 41393297, 2025). "LRP5 expression in APs and WAT declines with age and accordingly, LRP5 GoF mutation carriers were protected from the lower-body fat loss associated with aging, which we propose is the osteoporosis equivalent in WAT." (PMID 40000740, 2025). "Mutations resulting in the loss of function of LRP5 are associated with osteoporosis, while gain-of-function mutations in LRP5 are linked to increased BMD." (PMID 40149584, 2025). "We report two cases of AFFs in nine-year-old identical twins with early-onset osteoporosis secondary to a lipoprotein receptor-related protein 5 (LRP5) gene mutation." (PMID 40821177, 2025).
osteoporosis (continued). "For example, mutations in LRP5 lead to either a dominant form of osteoporosis with reduced BMD or a recessive form, osteoporosis-pseudoglioma syndrome, which is more severe and associated with additional phenotypes." (PMID 40772209, 2025). "Monogenic forms, often syndromic, were linked to mutations in genes such as COL1A1, COL1A2, and WNT1, whereas multifactorial osteoporosis, particularly postmenopausal, was associated with variants in LRP5, SOST, VDR, and other GWAS-identified loci." (PMID 40772209, 2025). "In the genetic study on 1,198 Chinese Han individuals, LRP5 rs11228240 reduced osteoporosis risk, while AXIN1 variants (rs9921222, rs2301522) increased susceptibility, underscoring genetic modulation of Wnt signaling in osteoporosis." (PMID 41282593, 2025). "The features of the Spondylo-ocular syndrome overlap with those resulting from homozygous variants in LRP5, the Osteoporosis-Pseudoglioma syndrome." (PMID 38942908, 2024). "Initially research focussed on the autosomal recessive syndrome of Osteoporosis Pseudoglioma plus or minus Mental retardation in which genomic variants in LRP5 were well characterized." (PMID 38942908, 2024). "Osteoporosis-pseudoglioma syndrome is a specific type of osteoporosis linked to loss-of-function mutation in LRP5 encoding for the Wnt co-receptor LRP5." (PMID 38580623, 2024). "In humans, recessive loss-of-function mutations in the LRP5 gene, a co-receptor in the Wnt signaling pathway, lead to osteoporosis-pseudoglioma syndrome." (PMID 39791729, 2024). "Metabolic bone disorder clinical exome screening (limited panel of metabolic bone disorders and gastrointestinal disorders) was undertaken and revealed a class 4 likely pathogenic variant in the LRP5 gene known to cause osteoporosis." (PMID 38404691, 2024). "The enhancement of osteoblast function depends on the successful initiation and activation of the Wnt/β-catenin signaling pathway, with mutations in the LRP5 gene within this pathway recognized as a significant contributor to the development of osteoporosis." (PMID 39421618, 2024). "Biallelic mutations in the WNT receptor, LRP5, lead to severe childhood-onset osteoporosis and blindness, while heterozygous loss-of-function variants lead to milder forms of osteoporosis, often presenting later in childhood or in adulthood." (PMID 37668887, 2024). "The positive establishment and activation of the Wnt/β-catenin signaling pathway is crucial for the value-added of osteoblasts, and mutations in the LRP5 gene within this pathway have been identified as an important cause of osteoporosis." (PMID 38027200, 2023). "In humans, inherited bone mass changes and skeletal diseases such as osteoporosis were demonstrated to be caused by various variants in the LRP5 gene." (PMID 38033331, 2023). "Patient S9 was suspected of monogenic osteoporosis and had a missense variant c.3220G > T (p.Val1074Phe) in LRP5." (PMID 37076969, 2023). "Homozygosity for loss-of-function mutations in LRP5 was identified as the underlying cause of osteoporosis pseudoglioma, a syndrome characterized partly by early-onset, severe osteoporosis." (PMID 37612291, 2023). "Variants in LRP5 were also described in osteoporosis pseudoglioma syndrome, combining severe osteoporosis and eye abnormalities." (PMID 37283650, 2023). "Many of these are aimed at treating osteoporosis by mimicking the increase in canonical WNT signaling seen in patients with gain-of-function LRP5 variants." (PMID 37895195, 2023). "A recent study on a large cohort (372 individuals) of subjects with early-onset osteoporosis identified rare LRP5 or LRP6 variants in 8.3%." (PMID 34236445, 2022). "In humans, loss-of-function mutations in LRP5 cause Osteoporosis-Pseudoglioma syndrome, a low bone mass disorder, while gain-of-function missense mutations have been observed in individuals with high bone mass." (PMID 36120446, 2022).
osteoporosis (continued). "Several studies have identified individuals with childhood or early adulthood onset symptomatic osteoporosis caused by rare heterozygous LRP5 variants." (PMID 34236445, 2022). "LRP5 mutation was not only reported in osteoporosis, but has also been associated with parathyroid tumors." (PMID 35586626, 2022). "On the other hand, loss-of-function mutations in the canonical Wnt co-receptors LRP5/6 have been identified as a cause of osteoporosis pseudoglioma syndrome." (PMID 36497192, 2022). "Several GWAS studies identified LRP5 as a major risk locus for osteoporosis-related phenotypes in the general population." (PMID 36120446, 2022). "In humans, recessive loss-of-function mutations in LRP5, a co-receptor in the Wnt signaling pathway, cause osteoporosis-pseudoglioma syndrome." (PMID 36120446, 2022). "In postmenopausal Romanian women with osteoporosis, there is a close association between LRP5 and SOST polymorphisms." (PMID 35785219, 2022). "Loss of function missense mutation in LRP5 causes severe osteoporosis, a condition called osteoporosis-pseudoglioma syndrome (OPPG)." (PMID 35563488, 2022). "The proteins encoded by low-density-lipoprotein receptor-related protein 5 (LRP5) are associated with osteoporosis-pseudoglioma syndrome, and the Norrie disease protein (NDP) is associated with Norrie disease." (PMID 36411543, 2022). "Rare pathogenic LRP5 variants have also been described in patients with pregnancy- and lactation-associated osteoporosis (PLAO)." (PMID 34236445, 2022). "Because LRP5/6 acts as a coreceptor for Wnt proteins, loss of function of LRP5/6 leads to osteoporosis (osteoporosis-pseudoglioma syndrome (OPPG)), and a specific point mutation in this same receptor results in high bone mass." (PMID 34943845, 2021). "Nevertheless, osteopenia/osteoporosis is clearly a multifactorial condition in which LRP5 mutations are one of the multiple possible causes." (PMID 34639175, 2021). "Of 11 subjects with rare variants in LRP5, the patient with p.R1135C had a referred family history of osteoporosis." (PMID 34639175, 2021). "LRP5 maps to chromosome 11q12-13 and it has been frequently investigated in subjects with skeletal diseases as a candidate susceptibility factor for osteoporosis, as variants in this gene have reached genome-wide significance levels (p < 1.0 × 10−21)." (PMID 34639175, 2021). "In humans, inhibitory mutations of LRP5 cause osteoporosis, whereas activating mutations of LRP5 or loss of SOST results in osteosclerosis." (PMID 34031510, 2021). "Lrp5 has diverse roles in the maintenance of bone mass, eye development, and cholesterol homeostasis, and has been implicated in osteoporosis." (PMID 34794440, 2021). "Genome-wide association studies identified several genes that favor osteoporosis, including low-density lipoprotein receptor-related protein 5 (LRP5) and receptor activator of NF-κβ (RANK)." (PMID 34680509, 2021). "Of note, inactivation of the gene for LRP5 results in osteoporosis–pseudo-glioma syndrome, while gain-of-function mutation in LRP5 leads to a syndrome of hereditary high bone density." (PMID 34201396, 2021). "Loss-of-function mutations in LRP5 explain the low bone mass in osteoporosis-pseudoglioma syndrome and other missense mutations in the same domain were identified in high bone mass phenotypes." (PMID 34938269, 2021). "In recent decades, genome-wide association studies (GWAS) focusing on the LRP5 gene have confirmed a close relationship of its genotypes with osteoporosis." (PMID 33101205, 2020). "For instance, gain-of-function mutations in the LRP5 gene result in drastic increases in bone mass, while loss-of-function mutations cause decreases in bone mass, i.e., osteoporosis-pseudoglioma syndrome." (PMID 33162933, 2020). "Homozygous WNT1 pathogenic variants are a cause of OI type XV, whereas heterozygous pathogenic variants and variants in the LRP5 gene, associated with the Wnt pathway, cause osteoporosis." (PMID 33228694, 2020).